TFE3 (transcription factor binding to IGHM enhancer 3)
Diseases named in the same sentence as TFE3 in open-access papers (continued):
Sharing a sentence is not in itself a finding about the gene and the disease.
renal carcinoma (continued). "We found that GPNMB expression, which is regulated by MiTF, was greatly elevated in renal cancer cells harboring either TFE3 translocations or FLCN inactivation." (PMID 21209915, 2010). "Renal carcinoma with Xp11.2 translocation involving TFE3 gene fusion was first recognized as a distinct entity in 2004, and later in 2016, it was classified in the category of renal carcinomas with MiT gene translocations, alongside renal carcinoma with transcription factor B (TFB) gene fusion." (PMID 39851801, 2025). "Further studies should be conducted regarding the optimal treatment for patients with renal carcinoma associated with Xp11.2 translocation/gene fusion TFE3, considering that the literature data are lacking." (PMID 39851801, 2025). "Indeed recent advances have identified new entities in renal carcinoma with clear cell morphology and VHL wild type phenotype such as TFE3-rearranged RCC, ELOC (formely TCEB1)-mutated RCC or clear cell renal papillary tumor." (PMID 40771659, 2025). "Several molecularly defined renal carcinomas have also been reported in the context of FDG-PET findings.TFE3-rearranged RCC, which arises from fusions between the TFE3 gene and various other genes on different chromosomes, commonly occurs in children and young adults." (PMID 40193012, 2025). "Here, we find another mode of TFE3 activation in human renal carcinoma." (PMID 36935008, 2023). "Interestingly, TFE3 depletion inhibited proliferation of a renal carcinoma cell line, whereas ectopic overexpression of MITF in the TFE3-depleted cells rescued proliferation." (PMID 32881934, 2020). "Whether or not the modulation of p21 also plays a role in the oncogenic activity of TFEB/TFE3-induced renal carcinoma, will be the subject of future studies." (PMID 32397616, 2020). "The role of AGS11/TFE3 in this transcriptional activation process may warrant further evaluation in this specific type of renal cancer." (PMID 26300785, 2015). "Thus it is likely that elevated TFE3 transcriptional activity as a consequence of FLCN inactivation contributes to the development of renal carcinoma." (PMID 21209915, 2010). "While TFE3 expression appears to be practically ubiquitous in normal tissues, it is expressed at extremely low levels, and tumors known to have TFE3 gene fusions, such as ASPSs and uncommon pediatric renal carcinomas, are the only places where high nuclear expression of TFE3 is observed." (PMID 38962626, 2024). "Immunohistochemically, this type of renal cancer exhibits the following characteristics: PAX+, Vimentin+, CK7–, CA IX–, CD10+, and TFE3+." (PMID 39851801, 2025). "This TFE3 fusion-driven OXPHOS program, together with heightened glutathione levels found in renal cancers, renders tRCCs sensitive to reductive stress – a metabolic stress state induced by an imbalance of reducing equivalents." (PMID 39149323, 2024). "Here we report that TFE3 fusions transcriptionally rewire tRCCs toward oxidative phosphorylation (OXPHOS), contrasting with the highly glycolytic metabolism of most other renal cancers." (PMID 39149323, 2024). "It has been demonstrated that aberrant and strong nuclear expression of TFE3 is seen exclusively in tumours which contain the TFE3 gene fusions, such as ASPS and rare paediatric renal carcinomas." (PMID 26837430, 2016). "Positive staining for the TFE3 protein is specific to renal carcinoma with Xp11.2 translocation and is not found in conventional renal carcinomas." (PMID 39851801, 2025). "However, using a mouse xenograft generated using a cell line derived from a renal cancer patient with BHD syndrome, we found that silencing of either TFEB or TFE3 was able to rescue the tumorigenic phenotype." (PMID 40189703, 2025). "Transcription factor E3 (TFE3) oncofusions are frequently detected in the Microphthalmia transcription factor (MiT) family translocation renal cell carcinoma (tRCC), a rare pediatric renal cancer with limited treatment options." (PMID 41027885, 2025).
renal carcinoma (continued). "TFE3-RCC and TFEB-RCC, classified as molecularly defined renal carcinomas in the current WHO classification, may also express HMB45 but are negative for CK7." (PMID 40584698, 2025). "For example, the melanotic Xp11 translocation renal cancer has TFE3 rearrangement, which is not observed in the pigmented PEComa." (PMID 27858882, 2016). "Further support for the primacy of TFE3 comes from the detection of alternate TFE3 fusion proteins (PRCC-TFE3, PSF-TFE3, NONO-TFE3) in a subset of renal carcinomas." (PMID 19146682, 2009).
translocation renal cell carcinoma (32 papers, 2013 to 2026). "Xp11.2 translocation renal cell carcinoma (tRCC) is mainly caused by translocation of the TFE3 gene located on chromosome Xp11.2 and is characterized by overexpression of the TFE3 fusion gene." (PMID 30849994, 2019). "Xp11.2 translocation renal cell carcinoma (tRCC), first reported in 1988, is characterized by a pathognomonic chromosomal translocation of transcription factor E3 (TFE3), which causes fusion of the TFE3 gene with a variety of partner genes." (PMID 34784933, 2021). "TFE3 translocation renal cell carcinoma (tRCC), an aggressive kidney cancer driven by TFE3 gene fusions, is frequently misdiagnosed owing to morphologic overlap with other kidney cancer subtypes." (PMID 41623182, 2026). "TFE3 fusion proteins are the oncogenic drivers of translocation renal cell carcinoma but their mechanism of action remains poorly understood." (PMID 40148585, 2025). "Translocation renal cell carcinoma (tRCC) is a rare subtype of kidney cancer characterized by genetic translocation events frequently involving transcription factor TFE3 or more rarely TFEB." (PMID 40148585, 2025). "The oncogenic mechanisms by which TFE3 fusion proteins drive translocation renal cell carcinoma (tRCC) are poorly characterized." (PMID 40148585, 2025). "Translocation renal cell carcinoma (tRCC) is an aggressive subtype of kidney cancer driven by TFE3 gene fusions, which act via poorly characterized downstream mechanisms." (PMID 39149323, 2024). "A previous study showed that CTSK and TFE3 remain the most sensitive and specific biomarkers for Xp11 translocation renal cell carcinoma." (PMID 36005209, 2022). "TFE3-translocation renal cell carcinoma (TFE3-tRCC) is a rare subtype of kidney cancer, characterized by Xp11.2 translocations resulting in TFE3 fusion with various partner genes." (PMID 34489456, 2021). "Xp11.2 translocation renal cell carcinoma (tRCC) is defined by translocation of the transcription factor E3 (TFE3) gene located on chromosome Xp11.2." (PMID 34784933, 2021). "Xp11.2 translocation renal cell carcinoma (Xp11.2 tRCC), as an independent subset of RCC in the 2016 WHO classification, is characterized with poor prognosis of patients caused by high expression of transcript factor E3 (TFE3) fusion gene." (PMID 35042525, 2022). "An interesting study reported 39 cases of genetically confirmed translocation renal cell carcinoma patients; six (15%) of these patients had a history of receiving chemotherapy at childhood, which indicated that chemotherapy may increase the possibility of TFE3 translocation." (PMID 26872381, 2016). "An aggressive subtype termed translocation renal cell carcinoma (tRCC) is notably more difficult to detect than the common type, clear-cell RCC, in part due to interindividual variability of gene fusions of the transcription factor TFE3, the driving factor in tRCC." (PMID 41623175, 2026).
epithelioid hemangioendothelioma (25 papers, 2015 to 2025). A low-grade malignant blood vessel neoplasm. "One such fusion protein, YAP-TFE3, occurs in 10 to 20% of epithelioid hemangioendotheliomas, a vascular tumor that is caused by fusion of the N terminus of either YAP or TAZ with TFE3 or CAMTA1, respectively." (PMID 40712036, 2025). "Interestingly, these fusions lead to the mutually exclusive nuclear accumulation of CAMTA1 or TFE3, making IHC a reliable read out for both variants of epithelioid hemangioendothelioma." (PMID 33114111, 2020). "Some epithelioid hemangioendothelioma demonstrate a fusion of WWTR1 and CAMTA1CAMTA1, and immunohistochemistry for CAMTA1 can be positive, while others with YAP1-TFE3 fusion show nuclear expression of TFE3." (PMID 37510144, 2023). "According to the literature, TFE3 nuclear-positive epithelioid angioendothelioma with or without abnormal TFE3 gene expression is different from classic epithelioid angioendothelioma, which has obvious vascular formation." (PMID 37528481, 2023). "In epithelioid hemangioendothelioma, a rare cancer that grows in the blood vessels, cancerous growth can be driven by a version of TAZ fused to the protein CAMTA1, or a version of YAP fused to the protein TFE3." (PMID 33913810, 2021). "Recently, a YAP and transcription factor E3 (TFE3) (YAP-TFE3) fusion gene, and a TAZ and calmodulin-binding transcription activator 1 (CAMTA1) (TAZ-CAMTA1) fusion gene were reported in cases of epithelioid hemangioendothelioma, a rare type of soft tissue sarcoma." (PMID 31100975, 2019). "FISH results were negative for c-Myc amplification and for TFE3 translocation, which ruled out epithelioid angiosarcoma (EAS) and epithelioid hemangioendotheliomas (EHEs)." (PMID 31311568, 2019).
melanoma (25 papers, 2010 to 2026). A malignant, usually aggressive tumor composed of atypical, neoplastic melanocytes. "Previous studies have demonstrated that TFE3 is a transcription factor expressed in melanoma, which is closely associated with MITF, and plays a crucial role in regulating the sensitivity of cells to iron-induced cell death." (PMID 39440241, 2024). "Consistent with previous observations in melanoma, in TCGA melanoma cohort, TFE3 mRNA was inversely correlated with MITF, while a moderate anti-correlation was also noted between MITF and TFEB." (PMID 41275493, 2025). "This coordination links mTORC1 signaling with the endosomal–lysosomal system, making MITF a key regulator of melanoma plasticity and progression via control of TFE3, TFEB, and endosomal–lysosomal pathways." (PMID 41155412, 2025). "Immunohistochemical staining showed strong positivity for transcription factor binding to IGHM enhancer 3 (TFE-3) and was partially positive for Human Melanoma Black (HMB-45), consistent with a diagnosis of perivascular epithelioid cell tumor (PEComa)." (PMID 33251071, 2020). "Like MITF, the TFEB and TFE3 genes are expressed in melanoma cells as well as in melanoma tumors, albeit at lower levels." (PMID 32881934, 2020). "In this study, we show that the MITF, TFEB and TFE3 transcription factors are all produced in melanoma cells, albeit at different levels." (PMID 32881934, 2020). "The related transcription factors TFEB and TFE3 regulate lysosomal activity and autophagy processes known to be important in melanoma." (PMID 30705290, 2019). "Our results suggest that MITF and the related factors TFEB and TFE3 have separate roles in regulating a starvation-induced autophagy response in melanoma." (PMID 30705290, 2019). "So far, there is limited evidence to show the over expression of TFE3 in solid tumors other than papillary renal carcinoma and melanoma." (PMID 25485635, 2014). "Although the molecular weight of TFE3 is 62 kDa, it was reported that TFE3 protein from B16 melanoma cells and mouse splenocytes migrates close to 72 kDa." (PMID 21209915, 2010). "Similarly, PPARGC1A (PGC1A), a master regulator of mitochondrial biogenesis regulated by MITF in melanoma, also displayed multiple TFE3 fusion binding sites at the promoter and putative upstream and downstream regulatory elements in the tRCC lines." (PMID 40148585, 2025). "The same effect was observed for TFEB and TFE3 (another MITF family member) in non-melanoma cells." (PMID 33802847, 2021). "This role of TFEB and TFE3 in immune response in melanoma needs to be explored further, as this raises important therapeutic questions about their role in immunotherapy, a key treatment option for melanoma." (PMID 30705290, 2019). "Interestingly, TFEB and TFE3 show strong correlation with genes involved in the immune response in these tumors, implying a distinct role for these factors in melanoma tumors." (PMID 30705290, 2019). "The role and importance of localisation and heterodimerization of MITF, TFEB and TFE3 in melanoma cells remains to be explored and may reveal why MITF regulates a distinct set of genes compared to the other factors." (PMID 30705290, 2019). "TFE3 amplification is reportedly correlated with poor prognosis of melanoma." (PMID 26872381, 2016). "Here, we reveal the functional specialization of MITF, TFE3, and TFEB and their impact on melanoma progression." (PMID 41275493, 2025). "Meanwhile, in MITF-low invasive melanoma, transcription factor EB (TFEB) and TFE3 drive lysosomal biogenesis and function to support tumor growth and invasiveness through nutrient recycling and metabolic adaptation." (PMID 41155412, 2025). "We also observed that TFE3, a transcription factor from the same family 21, was slightly increased at mRNA and protein levels in both WM1716 and WM1745 short-term culture melanoma cell lines." (PMID 38750105, 2024).
melanoma (continued). "Particularly, in the 501Mel and Skmel28 human melanoma cell lines used in this study, MITF is highly expressed whereas TFEB and TFE3 are expressed at considerably lower levels." (PMID 32881934, 2020). "MITF thus has a regulatory role within lysosomal function and autophagy in melanoma tumors, distinct from the related TFEB and TFE3 factors." (PMID 30705290, 2019). "Transcription factor E3 (TFE3), a member of the MiTF/TFE family of transcription factors, plays an important role in papillary renal carcinoma and melanoma." (PMID 25485635, 2014). "Diagnosis was established based on morphology and strong nuclear TFE3 immunoreactivity, supported by additional immunohistochemical (IHC) markers including cluster of differentiation 10 (CD10), Melan-A, human melanoma black 45 (HMB45), vimentin, carbonic anhydrase IX (CAIX), and cytokeratins." (PMID 42220779, 2026). "Tumor cells showed diffuse expression of melanocytic markers (HMB45 and melanoma cocktail), cathepsin K and TFE3 in the absence of smooth muscle markers." (PMID 41790187, 2026). "Publicly available ChIP-seq data for MITF in 501Mel and Colo829 human melanoma cells were analyzed in order to determine if MITF might be involved in directly regulating its own expression or that of TFEB and TFE3." (PMID 32881934, 2020). "MITF, TFEB and TFE3 are expressed to some extent across melanoma tumors and cell lines, whereas TFEC is not." (PMID 32881934, 2020). "In MITF-high early-stage melanoma, MITF promotes proliferation and limits invasiveness by activating the mechanistic target of rapamycin complex 1 (mTORC1), which sequesters transcription factor E3 (TFE3) in the cytoplasm and directs it for lysosomal degradation, reducing its pro-invasive effects." (PMID 41155412, 2025). "In our cohort, while tumors that have MiTF pathway activation without TFE3 rearrangement (i.e., granular cell tumor and melanoma) demonstrated TRIM63 RNA hybridization, they generally did so at a lower level than that of ASPS, with lower average H-scores (p < 0.05)." (PMID 38393424, 2024). "However, the expression of MITF negatively correlates with TFEB and TFE3 expression, raising the question whether MITF regulates a different set of lysosomal genes than the other factors in melanoma." (PMID 30705290, 2019). "Moreover, our case involved the complete absence of morphological indications of spindle neoplastic cell differentiation and the presence of nuclear labeling of TFE3 in immunohistochemical analysis; these features are not typical of malignant melanoma." (PMID 30103811, 2018). "The finding that the MiT-TFE factors are co-expressed in melanoma cells and tumors, together with recent evidence pointing to a role of MITF in the regulation of lysosomal and autophagy-related genes, similar to TFEB and TFE3, may suggest an overlap in function or cooperation between these factors." (PMID 32881934, 2020). "Here, we investigate the role of TFEB and TFE3 in cells that also express MITF to better understand the potential of these related transcription factors to exhibit distinct and non-redundant roles in gene expression and melanoma progression." (PMID 41275493, 2025). "These quantitative thresholds in a calibrated assay would offer some objectivity and additional specificity that is lacking when interpreting TFE3 and cathepsin K IHC in the workup of cases of ASPS for which tumors like granular cell tumor and melanoma remain in the differential consideration." (PMID 38393424, 2024).
kidney cancer (21 papers, 2017 to 2026). Primary or metastatic malignant neoplasm involving the kidney. "The larger collection of non-type-I papillary RCCs is composed of type II papillary renal carcinomas, including duct carcinomas, medullary renal cell carcinomas, the MiTF kidney cancers (TFE3, TFEB), and hereditary leiomyomatosis RCC-associated kidney cancers." (PMID 33205131, 2020). "Interestingly, TFE3 translocations and gene duplications (i.e., gain-of-function variants) are a relatively common cause of kidney cancer, associated with high mTORC1 activity, thus mimicking the effects of FLCN deletion in BHD syndrome." (PMID 35358174, 2022). "We find that TFE3 is constitutively localized to the cell nucleus in human and mouse kidney cancer, where it increases autophagic gene expression and promotes cell autophagy as well as proliferation." (PMID 36935008, 2023). "Immunostaining showed TFE3 also mainly localized to the nucleus in RENCA mouse kidney cancer cells and decreased TFE3 signal in TFE3-KD cells indicated specificity of the signal." (PMID 36935008, 2023). "TFE3-tRCC was first recognized in the World Health Organization (WHO) classification of kidney cancers in 2004." (PMID 35886994, 2022). "In 2004, TFE3-tRCC was recognized as a specific entity in the World Health Organization’s (WHO’s) kidney cancers." (PMID 35886994, 2022). "Multiple genes linked with kidney cancer, including the VHL, MET, FLCN, fumarate hydratase, succinate dehydrogenase, TSC1, TSC2, and TFE3, were identified by genomic studies and have significantly altered the ways in which patients with kidney cancer are managed." (PMID 29254180, 2017). "In addition, silencing of either TFEB or TFE3 rescued tumorigenesis in mouse xenografts generated using a cell line derived from a kidney cancer patient with BHD syndrome, indicating that TFEB and TFE3 are the main drivers of tumorigenesis in multiple tissues." (PMID 40189703, 2025). "TFE3-translocation renal cell carcinoma (TFE3-tRCC) is a rare and heterogeneous subtype of kidney cancer with no standard treatment for advanced disease." (PMID 34489456, 2021). "TFE3-translocation renal cell carcinoma (TFE3-tRCC) is a rare subtype of kidney cancer with no standard treatment options for the advanced disease." (PMID 34489456, 2021). "Notably, SFPQ, a close family member of NONO and PSPC1, has been identified as essential for the survival of both TFE3 fusion and non-fusion kidney cancer cells." (PMID 41027885, 2025). "Our work illuminates actionable metabolic features driven by the TFE3 fusion in tRCC that are distinct from other RCC subtypes, offering hope that molecularly-directed therapies can be advanced to specifically target the biology of this aggressive subtype of kidney cancer." (PMID 39149323, 2024).